LRRK2 (leucine rich repeat kinase 2)
Diseases named in the same sentence as LRRK2 in open-access papers (continued):
Sharing a sentence is not in itself a finding about the gene and the disease.
leprosy (64 papers, 2010 to 2026). Leprosy is a chronic infectious disease affecting primarily the skin and peripheral nervous system. "A compelling example is the LRRK2 R1628P variant, which has been associated with T1R-protection when comparing T1R-affected and T1R-free leprosy patients." (PMID 41430073, 2025). "First, we focused on the replication of the association of PD-linked genes PRKN and LRRK2 with T1R in Vietnamese leprosy patients." (PMID 41430073, 2025). "By applying unbiased WGS analysis on a family with monozygotic twins with extreme early onset leprosy, we identified three coding variants in the LRRK2 and NOD2 genes as strong candidates for contributing to early onset leprosy susceptibility." (PMID 36972292, 2023). "While our study was motivated by early onset leprosy, it is likely that the additive interactions of the LRRK2 and NOD2 variants and their effect on key inflammatory host pathways are also valid in PD and CD patients." (PMID 36972292, 2023). "Our present data extended the concept of antagonistic pleiotropy of LRRK2 mutations to leprosy and PD/CD." (PMID 36972292, 2023). "The LRRK2 loci that showed suggestive association with leprosy in our previous study reached genome‐wide significant level in this study." (PMID 38020709, 2023). "Since leprosy is an infectious disease, a weakened inflammatory host response mediated by the LRRK2 DM and NOD2 R702W is expected to increase susceptibility." (PMID 36972292, 2023). "Beyond PD, genome-wide association studies have identified LRRK2 as a disease risk locus in a number of other diseases, including leprosy and inflammatory bowel disease." (PMID 37698513, 2023). "In previous work, it was shown that the LRRK2 1628P mutation was a risk factor for leprosy but protective for T1R." (PMID 36972292, 2023). "Although the mechanism underlying the link between LRRK2 and CD, leprosy and cancer is still unclear, this substantial association with peripheral diseases suggests a probably equally important role of LRRK2 throughout the body, both within and beyond the CNS." (PMID 36716346, 2023). "Our present results provide the first evidence for a role of LRRK2 in leprosy risk outside of East Asia by invoking trans-ethnicity LRRK2 amino acid mutations." (PMID 36972292, 2023). "Intriguingly, the same LRRK2 coding variants identified in the leprosy family have been implicated in reduced susceptibility to PD and CD while NOD2 R702W is a risk factor for both CD and PD." (PMID 36972292, 2023). "In this analysis we included variants associated with leprosy susceptibility at genome-wide significance in other populations, alongside variants at LRRK2 and PRKN, and pathogenic variants at NOD2." (PMID 36121873, 2022). "LRRK2 was identified by a genome-wide association study (GWAS) as one of the leprosy susceptibility genes in the Han Chinese population." (PMID 36076909, 2022). "Considering that LRRK2 is implicated in chronic diseases such as PD, leprosy and IBD, the role of LRRK2 in chronic inflammatory models and autoimmunity warrants further investigation." (PMID 33291304, 2020). "The association of LRRK2 to inflammation is also supported from reports linking LRRK2 polymorphisms to inflammatory conditions such as leprosy and inflammatory bowel disease (IBD)." (PMID 33291304, 2020). "Nevertheless, some of these SNPs, such as rs3761863 in LRRK2 had been associated with a type-1 reaction, which is considered an endophenotype of leprosy." (PMID 32433683, 2020). "GWAS analysis of a Han Chinese cohort first suggested an association of LRRK2 rs1873613 with Leprosy per se, and in particular a significant association of LRRK2 rs1491938 with the multibacillary form of leprosy." (PMID 32210756, 2020). "By contrast, similarities between leprosy and tuberculosis (TB), the third inflammatory disease linked to LRRK2, were already well established when this connection was reported via a meta-analysis of nine separate GWAS investigations of TB patients." (PMID 31864390, 2019).
leprosy (continued). "It has been reported that a specific mutation in the LRRK2 gene is associated with acute inflammation in both leprosy and CD cases, supporting the assumption that these diseases share common pathological mechanisms." (PMID 29755459, 2018). "The risk of certain types of cancer appears to be modulated by LRRK2-PD mutations; moreover, noncoding polymorphisms in the LRRK2 locus are associated with an increased risk of leprosy and inflammatory bowel disorder." (PMID 28202669, 2017). "Several groups have evaluated the association of the LRRK2 gene with leprosy susceptibility but results were inconsistent." (PMID 26844546, 2016). "Here, we show that variants overlapping the LRRK2 gene, reported as suggestive leprosy per se susceptibility factors in a previous genome-wide association study, are preferentially associated with T1R." (PMID 26844546, 2016). "Since there is evidence that host genetic factors predispose leprosy patients to T1R, we have conducted a candidate gene study to test if LRRK2 gene variants are T1R risk factors." (PMID 26844546, 2016). "Given that T1R affects different proportions of leprosy cases according to the studied population, we wondered if inconsistencies in LRRK2 association with leprosy per se were due to different proportions of T1R in each setting." (PMID 26844546, 2016). "In the reported GWAS study from Han Chinese population, the LRRK2 rs1873613A allele was observed as a major allele whereas the rs1873613G variant is a minor allele and confers decreased risk towards leprosy in Chinese patients." (PMID 24015287, 2013). "Distribution of investigated NOD2, RIPK2, and LRRK2 variants in clinically classified leprosy patients and controls." (PMID 24015287, 2013). "The LRRK2 rs1873613A minor allele and respective rs1873613AA genotypes were significantly associated with an increased risk whereas the LRRK2 rs1873613G major allele and rs1873613GG genotypes confer protection in paucibacillary and leprosy patients." (PMID 24015287, 2013). "A key area of research is the identification of the molecular mechanisms linking variants in the LRRK2 region with modified risk for PD, CD and leprosy." (PMID 23967090, 2013). "The association study of LRRK2 rs1873613A/G variant with leprosy was also conducted in a Vietnamese population, however the association was not statistically significant." (PMID 24015287, 2013). "However, due to the variant-dependent effects of LRRK2 in leprosy and its associated endophenotypes, a more tailored selection of candidate compound will be necessary." (PMID 41430073, 2025). "However, the LRRK2 M2397T mutation is connected to altered biological function of LRRK2 and associated with leprosy and excessive inflammatory responses in leprosy." (PMID 36972292, 2023). "Additionally, LRRK2 mutations were reported to aggravate the type-1 reaction in leprosy, and the innate immune response against Mycobacterium tuberculosis." (PMID 36716346, 2023). "Hence, the two LRRK2 variants were considered the top candidates contributing to the early onset leprosy phenotype." (PMID 36972292, 2023). "Less common LRRK2 missense mutations also modulate kinase activity of LRRK2 by varying amounts; these represent but a few of the almost 100 known LRRK2 mutations, some of which also modulate risk of a form of inflammatory bowel disease and a form of leprosy." (PMID 36388213, 2022). "Notably, variants in LRRK2 have been observed to increase susceptibility to Mycobacterium leprae infection, the microbe causative of leprosy, characterised by peripheral neuron damage." (PMID 34397087, 2021). "Polymorphisms in the LRRK2 gene have been linked to increased susceptibility to leprosy." (PMID 32508566, 2020). "Thus, as for PD and IBD, the genetics underlying LRRK2 susceptibility to Leprosy or subsequent complications, likely involves a complex interplay of both risk and protective alleles." (PMID 32210756, 2020).
leprosy (continued). "Moreover, the association between leprosy and LRRK2 has been reported by a genome-wide association study (GWAS)." (PMID 32164260, 2020). "Interestingly, leprosy patients carrying a Lrrk2 missense variant are more prone to develop T1R with excessive inflammation of which IL-1β is one biomarker." (PMID 31921172, 2019). "Moreover, RIPK2 was validated in an Indian population, while LRRK2 was found to be associated with leprosy and the PB clinical form in Chinese and Indian population samples." (PMID 30116885, 2018). "Additionally, genomewide association studies have implicated LRRK2 in mycobacterial immunopathology and identified LRRK2 as a risk factor for inflammatory responses in leprosy, an infection by the intracellular pathogen Mycobacterium leprae as well as Mtb." (PMID 29789389, 2018). "In addition to neurons, LRRK2 is expressed in immune cells, and LRRK2 has been identified as one of the susceptibility genes for leprosy and Crohn’s disease." (PMID 30420654, 2018). "In like manner, genetic variation at NOD2 is reported to be associated with exacerbated inflammatory responses in leprosy reactions that could modulate downstream pathways, such as LRRK2 activation." (PMID 29755459, 2018). "Our finding that LRRK2 modulates Nod2 signaling in macrophages may explain how LRRK2 is involved in leprosy susceptibility." (PMID 27830463, 2017). "Hence, we first analyzed six LRRK2 SNPs (rs1873613, rs10878220, rs1491938, rs12820920, rs11174812 and rs11173979) described in association with leprosy per se by a GWAS in a Chinese population." (PMID 26844546, 2016). "We reasoned that this may reflect different proportions of leprosy patients with T1R in the different samples and that LRRK2 may in truth be a T1R susceptibility gene." (PMID 26844546, 2016). "Like TNFSF15, LRRK2 is a gene with an uncertain role in leprosy per se susceptibility." (PMID 26844546, 2016). "Second, a putative role of LRRK2 in the regulation of the immune response may justify the genetic association of LRRK2 with the susceptibility to inflammatory bowel disorder 10 and leprosy 11 other than with PD." (PMID 25899482, 2015). "Whereas major allele LRRK2 rs1873613G and homozygous genotype rs1873613GG were observed less frequently in patients compared to controls conferring a decreased risk of leprosy (OR = 0.61, 95% CI = 0.45–0.8, P = 0.0003 and OR = 0.56, 95% CI = 0.37–0.83, P = 0.0028, respectively)." (PMID 24015287, 2013). "Common variant associations in the LRRK2 region for PD, CD and leprosy." (PMID 23967090, 2013). "Furthermore, SNPs of LRRK2 and parkin were both associated with leprosy, a chronic infectious disease caused by Mycobacterium leprae." (PMID 22550610, 2012). "While we cannot exclude the presence of additional risk factors, the functional validation of LRRK2 and NOD2 variants implicates these amino acid changes in early onset leprosy." (PMID 36972292, 2023). "We found three amino acid changes in LRRK2 and NOD2 as candidate susceptibility variants for early onset leprosy." (PMID 36972292, 2023). "Combined, our results provide insight in the mechanism of leprosy susceptibility and highlight the contribution of specific amino acid alleles in NOD2 and LRRK2 in immune-mediated diseases." (PMID 36972292, 2023). "The loss of pro-inflammatory activity of LRRK2 and NOD2 has been linked to leprosy, PD, and CD, and LRRK2 enhances NOD2-mediated inflammatory cytokine production." (PMID 36972292, 2023). "Just a year later, linkage to LRRK2 was reported in GWAS of Chinese leprosy patients, a result that has been replicated in some but not all subsequent studies." (PMID 31864390, 2019). "Later, meta-GWASs identified the links between LRRK2 and CD and leprosy, suggesting a role for LRRK2 in immune regulation during infection and inflammation." (PMID 30669622, 2019). "Several genes have been associated with leprosy, such as NOD2, PARK2/PARCG, LRRK2, RIPK2, TNF/LTA/HLA, LACC1, IL10, TLR1, and microRNA (miR)-146a." (PMID 29755459, 2018).
leprosy (continued). "A genome-wide association (GWAS) in a Chinese sample provided the most comprehensive study of LRRK2 in leprosy." (PMID 26844546, 2016). "In this study, we investigated 211 clinically classified leprosy patients and 230 ethnically matched controls in Indian population by genotyping four variants in NOD2 (rs9302752A/G), LRRK2 (rs1873613A/G), RIPK2 (rs40457A/G and rs42490G/A)." (PMID 24015287, 2013). "Higher expression of LRRK2 is observed in macrophages and monocytes revealing its significance in the innate immune system and in leprosy per se." (PMID 24015287, 2013). "However, since the SNPs of LRRK2 and Parkin that are positively linked to inflammatory bowel diseases and leprosy differ from those linked to PD, it is unclear whether the molecular mechanisms are similar in α-synucleinopathies and other inflammation-related disorders." (PMID 22550610, 2012). "Other SNPs identified in the leprosy, tuberculosis and Crohn's-susceptibility studies have identified common genes including IRGM, LRRK2 and TNFSF15 suggesting that a theme of host microbial defence underlies the pathogenesis of these diseases." (PMID 20531959, 2010). "We first tested if the burden of rare protein-altering variants (defined as minor allele frequency [MAF] < 1%) in PRKN and LRRK2 differed between the 203 T1R-affected vs 200 T1R-free leprosy patients that had not been included in the previous study." (PMID 41430073, 2025). "Our results demonstrate how variants in LRRK2 and NOD2 can have a joint effect on different aspects of the immune response which may lead to early onset leprosy." (PMID 36972292, 2023). "Here, we investigated whether SNPs located in eleven genes: CCDC122/LACC1, IFNG, IL6, IL10, IL23R, LRRK2, NOD2, PACRG/PRKN, TLR1, TNF and TYK2 are associated to leprosy susceptibility in a population in the North of Brazil." (PMID 32433683, 2020). "Mutations in the leucine-rich-repeat kinase 2 (LRRK2) gene are associated with familial and sporadic cases of PD but are also found in immune-related disorders, such as inflammatory bowel disease (IBD) and leprosy." (PMID 32508566, 2020). "Therefore, our data provide a mechanistic link between inflammatory diseases such as inflammatory bowel disease, infectious diseases like leprosy and tuberculosis to LRRK2 function." (PMID 29789389, 2018). "The choice of LRRK2 was motivated by the fact that LRRK2 was associated with leprosy per se in some but not in other studies." (PMID 26844546, 2016). "Of the genes reported by the GWAS, the TNFSF15 and LRRK2 were the only leprosy susceptibility genes not validated for association with leprosy per se in a Vietnamese population." (PMID 26844546, 2016). "Our results also showed that LRRK2 rs1873613A/G variant significantly contributed to the development of paucibacillary leprosy but not multibacillary leprosy." (PMID 24015287, 2013). "However, meta-GWASs confirmed the link between LRRK2 and CD and leprosy, and it was hypothesized that LRRK2 acts as an immunomodulator in infection and inflammation." (PMID 40842999, 2025). "Thus, the leprosy susceptibility loci, including NOD2, RIPK2, TNFSF15, LACC1, LRRK2, IL12B, and HLA‐DR in phagocytes and IL23R, TYK2, and CSK in T cells, may interfere with the synergistic antimicrobial response between phagocytes and T cells." (PMID 38020709, 2023). "Similarly, the LRRK2 gene has mainly been implicated in leprosy susceptibility by association studies without any functional follow-up." (PMID 36972292, 2023). "Consequently, LRRK2 DM and NOD2 R702W had a cumulative effect on the reduction of N-glycolyl MDP-induced NF-κB activation and the variants carried by the early onset leprosy twins reduced NF-κB activation by approximately half compared to the wild-type variants expected in the general population." (PMID 36972292, 2023).
leprosy (continued). "Since both LRRK2 and NOD2 had been implicated in susceptibility to leprosy, CD and PD, and the corresponding proteins interact in-vivo in Paneth cells, we considered these two genes high priority candidates for exerting a joint effect on early onset leprosy susceptibility." (PMID 36972292, 2023). "Additional studies have supported the association of LRRK2 variants with Leprosy outcomes, however results are not always consistent across populations or Leprosy subtypes, with analysis presumably complicated by the lower sample sizes available for study of this rarer disease." (PMID 32210756, 2020). "Finally, LRRK2 is a negative regulator of inflammasome activation and an inducer of ROS production, two known mechanisms of immune defense against bacterial infections also modified by variants of LACC1, a gene consistently associated with leprosy." (PMID 30079069, 2018). "Variants near the LRRK2 gene have been associated with leprosy in some but not in other studies." (PMID 26844546, 2016). "We investigated the possible association of gene variants NOD2 (rs9302752A/G), LRRK2 (rs1873613A/G) and RIPK2 (rs40457A/G and rs42490G/A) that are vital for NOD2 signalling and subsequent activation of the NF-kB complex in a cohort of clinically classified leprosy patients." (PMID 24015287, 2013). "Fava and colleagues compared LRRK2 polymorphisms between Leprosy patient families affected and free from type-1 reactions, and concluded that the majority of GWAS reported LRRK2 polymorphisms were actually associated with T1R susceptibility within Leprosy, rather than Leprosy susceptibility per se." (PMID 32210756, 2020). "A recent genome wide study in Chinese leprosy patients has provided vital insights on the role of NOD2 (rs9302752A/G), LRRK2 (rs1873613A/G) and RIPK2 (rs40457A/G and rs42490G/A) variants in regulating the leprosy infection." (PMID 24015287, 2013). "We would not dispute the strength of this argument, but it does not reconcile the linkage of LRRK2 to leprosy and TB, which are in general not primarily gut disorders." (PMID 31864390, 2019). "Clinical subtypes of leprosy had no detectable impact on the eQTL effect of LRRK2 genotypes." (PMID 26844546, 2016). "A set of eQTLs for LRRK2 was observed in non-stimulated cell from leprosy patients." (PMID 26844546, 2016). "Interestingly, when these families were stratified by the T1R status of leprosy patients, variants located in two genes that could not be replicated for leprosy per se—TNFSF15 and LRRK2—were found associated with T1R." (PMID 30116885, 2018). "Similarly, 7 of the 9 SNPs significantly heterogeneous between T1R and leprosy were eQTLs in either whole blood, rs3774937 (NFKB1), rs10065637 (ANKRD55), rs11150589 (ITGAL) and rs2836878 (lncRNA ENSG00000235888) or multiple tissues, rs4664304 (LY75), rs113653754 (HLA-DQB1) and rs4768236 (LRRK2)." (PMID 28222097, 2017).